ZEB1 (zinc finger E-box binding homeobox 1)
Diseases named in the same sentence as ZEB1 in open-access papers (continued):
Sharing a sentence is not in itself a finding about the gene and the disease.
mesothelioma (2 papers, 2016 to 2025). A usually malignant and aggressive neoplasm of the mesothelium which is often associated with exposure to asbestos. "We first evaluated the expression of EMT molecules, which have been associated with prognosis in patients with mesothelioma, including Zeb1, YAP, ITGAV, and ACTA2." (PMID 40396518, 2025). "Xenoplanted D‐Meso‐Sonobe cells expressed nuclear Zeb1 and yes‐associated protein at the cancer invasion front and focally expressed integrin subunit alpha V and actin alpha 2, which are molecular phenotypes acquired by EMT in mesothelioma." (PMID 40396518, 2025).
metaplastic breast carcinoma (2 papers, 2023 to 2024). A group of invasive breast carcinomas characterized by the presence of an adenocarcinomatous component which is admixed with a dominant component that is composed of squamous cells, spindle cells, or mesenchymal cells. "In metaplastic breast cancers (MpBC), there is limited expression of TROP2, and downregulating transcription factor ZEB1 upregulates E-cad and TROP2, thus sensitizing cancers to TROP2 ADC sacituzumab govitecan (SG)." (PMID 37567892, 2023).
metastasis (2 papers, 2022 to 2024). The spread or migration of cancer cells from one part of the body (where they first appeared) to another. "ZEB1 level is also associated with vasculogenic mimicry and elevated ZEB1 is linked to a higher Gleason score and lymph node metastasis in Pca cells." (PMID 37305018, 2022).
metastatic prostate carcinoma (2 papers, 2015 to 2023). A carcinoma that arises from the prostate gland and has spread to other anatomic sites. "As stated, ZEB1 and E-cadherin are excellent markers; however, ZEB1 requires fixation of cells and E-cadherin is not specific enough to use as a stand-alone marker for metastatic prostate cancer." (PMID 25850653, 2015).
Mowat-Wilson syndrome (2 papers, 2014 to 2025). Mowat-Wilson syndrome (MWS) is a multiple congenital anomaly syndrome characterized by a distinct facial phenotype, intellectual disability, epilepsy, Hirschsprung disease (HSCR) and variable congenital malformations. "Finally, two cases had an established genetic diagnosis as follows: the case with mosaic 45XO/Turner syndrome and an additional case with Mowat-Wilson syndrome (ZEB1 mutation)." (PMID 41197831, 2025).
muscle atrophy (2 papers, 2018 to 2023). The loss of muscle tissue due to inactivity or disease. "The identification here of ZEB1 as an inhibitor of atrogene expression offers new approaches for therapies aimed at preventing or treating muscle atrophy." (PMID 30304480, 2018).
muscular dystrophies (2 papers, 2019 to 2023). "In turn, and in parallel with the mdx mouse, in human muscular dystrophies, ZEB1 was expressed not only in peripheral nuclei but also in centralized nuclei and in the cytoplasm of some fibers." (PMID 30910999, 2019). "Our results here established ZEB1 as an important factor in the regulation of both processes, thus potentially opening new avenues in the treatment of muscular dystrophies." (PMID 30910999, 2019). "Our results reveal an unexpected role for ZEB1 regulating the inflammatory and repair responses during muscle damage and can potentially open new strategies in the treatment of muscular dystrophies." (PMID 30910999, 2019). "Interestingly, CK levels in muscular dystrophy patients maintained a strong negative correlation with ZEB1 (Spearman’s ρ: −0.80)." (PMID 30910999, 2019).
myelodysplastic neoplasms (2 papers, 2023 to 2024). "The authors investigated circular RNA (circRNA) processing in patients with myelodysplastic neoplasms and observed upregulation of circRNAs derived from the zinc finger E‐box binding homeobox 1 (ZEB1) gene exclusively in patients with mutated splicing factor 3b subunit 1 (SF3B1)." (PMID 37408496, 2023).
myeloid leukemia (2 papers, 2019 to 2021). A clonal proliferation of myeloid cells and their precursors in the bone marrow, peripheral blood, and spleen. "Further studies are clearly required to determine the degree of synergy and crosstalk between ZEB1/2 and SNAI1 in AML as well as their common and unique underlying molecular roles in driving myeloid leukemia." (PMID 34550965, 2021).
Myocardial fibrosis (2 papers, 2023 to 2026). "This pathway mainly mediates the formation of myocardial fibrosis by promoting the expression of the Snail, Slug, and Zeb1 transcription factors during the EndoMT process." (PMID 35266091, 2023). "In a study by Xu, myocardial fibrosis was found to be considerably reduced in mice with endothelial Ets-1 deletion, which was accompanied by reduced EndoMT with decreased Snail, Slug, Twist, and ZEB1 expression." (PMID 35266091, 2023).
papilloma (2 papers, 2015 to 2019). A benign epithelial neoplasm that projects above the surrounding epithelial surface and consists of villous or arborescent outgrowths of fibrovascular stroma. "Since our general hypothesis is that transformation of benign papillomas to invasive SCC is causally linked to D2-mediated T3 activation, we evaluated the correlation of D2 expression in human tumors using the markers of EMT E-cadherin and ZEB-1, and the relative switch from papillomas to SCC." (PMID 31776338, 2019). "We validated by qRT-PCR the upregulation of EMT drivers, such as Zeb1, Zeb2, Twist and Prrx1, and EMT mediators, such as Wnt5a, Vcan, Ncadh and Mmp2 both in Nanog-papillomas and in Nanog-SCCs." (PMID 25988972, 2015). "In particular, Nanog-overexpressing papillomas show upregulation of several EMT mediators (Zeb1, Zeb2, Twist) and the master EMT inducer Prrx1, but not of the classical EMT inducers Snail/Slug." (PMID 25988972, 2015).
paraganglioma (2 papers, 2019 to 2021). A benign or malignant neoplasm arising from paraganglia located along the sympathetic or parasympathetic nerves. "This immature, multipotent phenotype is supported by constitutive amplification of NOTCH signaling genes and by loss of the microRNA-200s and -34s, which control NOTCH1, ZEB1, and PDGFRA in head and neck paraganglioma cells." (PMID 30813557, 2019).
postmenopausal osteoporosis (2 papers, 2021 to 2024). Metabolic disorder associated with fractures of the femoral neck, vertebrae, and distal forearm. "For example, ZEB1 was found to promote the generation of osteoblasts and inhibit the differentiation of osteoclasts, ultimately reducing the occurrence of postmenopausal osteoporosis." (PMID 39686556, 2024). "In conclusion, ZEB1 is an essential transcription factor in BMSC differentiation and may serve as a potential anabolic strategy for treating and preventing postmenopausal osteoporosis (PMOP)." (PMID 34109218, 2021).
serous borderline ovarian tumor (2 papers, 2014 to 2019). "More recently it has been demonstrated that EGF induces serous borderline ovarian tumors cell migration and invasion by activating EMT, which involves the activation of the ERK1/2 and PI3K/Akt pathways and, subsequently, Snail, Slug and ZEB1 expression." (PMID 24816687, 2014). "Another group found that EGF upregulates Snail1/2 and ZEB1 expression but does not affect Twist in serous borderline ovarian tumor cells (SBOT)." (PMID 31671862, 2019).
Sézary syndrome (2 papers, 2018 to 2021). "The characterization of ZEB1 abnormalities in Sézary syndrome fulfils the criteria of a canonical tumor suppressor gene." (PMID 30518749, 2018).
skin squamous cell carcinoma (2 papers, 2022 to 2025). A carcinoma arising from the squamous cells of the epidermis. "Notably, FSTL1 has been shown to induce EMT in skin squamous cell carcinoma by interacting with Zinc finger E-box binding homeobox 1 (ZEB1), enhancing tumor cell proliferation, migration, and invasion." (PMID 40808692, 2025).
abscesses (1 paper, 2023). "Micro-abscesses with depletion of apoptotic lymphocytes or necroptotic hepatocytes and infiltration by inflammatory cells were observed in white pulp of spleen or near vessels of liver from WT mice but not from Zeb1-dcKO mice." (PMID 37863917, 2023).
acute monocytic leukemia (1 paper, 2024). Acute monoblastic leukemia (AML-M5), is one of the most common subtypes of acute myeloid leukemia (AML) that is either comprised of more than 80% of monoblasts (AML-M5a) or 30-80% monoblasts with (pro)monocytic differentiation (AML-M5b). "A recent study has shown that enhanced Zeb1 expression in THP-1 acute monocytic leukemia cell line resulted in increased expression of M2 markers such as CD206, Arg1 and IL-10, concluding that Zeb1 induced aerobic glycolysis contributes to M2 polarization of macrophages." (PMID 38935134, 2024).
acute respiratory distress syndrome (1 paper, 2022). Progressive and life-threatening pulmonary distress in the absence of an underlying pulmonary condition, usually following major trauma or surgery. "However, during the early stages of acute respiratory distress syndrome (ARDS) induced in a mouse model by lipopolysaccharides (LPS), it was also shown that miR200b/c was downregulated, which was associated with an increment of their protein targets ZEB1 and ZEB2." (PMID 35743055, 2022).
adenomyosis (1 paper, 2022). The growth of endometrial tissue inside the muscular wall of the uterine corpus. "Among the examined samples, ZEB1 expression in epithelia was detected in 83.3% cases of adenomyosis, 80% cases of deep infiltrating endometriosis, and 16.7% cases of ovarian endometrioma." (PMID 36289723, 2022).
Alzheimer disease (1 paper, 2024). A progressive, neurodegenerative disease characterized by loss of function and death of nerve cells in several areas of the brain leading to loss of cognitive function such as memory and language. "The three TFs that have the highest cumulative weight in the models of these genes are SREBF1, SREBF2 and ZEB1, themselves associated with neuronal differentiation and neurodegenerative diseases like Alzheimer’s Disease or Huntington’s Disease." (PMID 38632500, 2024).
ampullary adenocarcinoma (1 paper, 2016). "The ampullary adenocarcinoma cell lines MDA-AMP7, AVC1, RCB1280, SNU478 and SNU869 were grown in standard culture medium and expression of KRT7, KRT20, CDX2, E-Cadherin and ZEB1 mRNA was measured by real-time PCR." (PMID 26951071, 2016).
anaplastic oligodendroglioma (1 paper, 2025). A WHO grade III oligodendroglioma with focal or diffuse malignant morphologic features (prominent nuclear pleomorphism, mitoses, and increased cellularity). "The highest percentage of ZEB1 mutations (6.25%) was associated with anaplastic oligodendrogliomas (grade 3)." (PMID 40679044, 2025).
anemia (1 paper, 2021). A reduction in the number of red blood cells, the amount of hemoglobin, and/or the volume of packed red blood cells. "Within 2 weeks of the final dose of tamoxifen, the Zeb1/2Δ/Δ mice had to be euthanized due to anemia, severe weight loss, and general ill health." (PMID 34550965, 2021). "Inducible KO of both Zeb1 and Zeb2 results in further blocks in hematopoiesis with dramatic increases in the number of HSPCs and such mice succumbing to lethal anemia/cytopenia within 2 weeks after tamoxifen-induced Zeb1/2 double knockout (iDKO)." (PMID 34550965, 2021).
aortic valve calcification (1 paper, 2023). "SCG2 and ZEB1 are significant influencing factors for aortic valve calcification, providing novel ideas for the diagnosis and treatment of CAVD patients." (PMID 36824454, 2023). "Moreover, in the present study, we investigated the effect of angiogenesis-related factors on aortic valve calcification and discovered that SCG2 and ZEB1 may be the key aortic valve calcification factors." (PMID 36824454, 2023).
apical periodontitis (1 paper, 2025). "Our study investigating human apical periodontitis lesions, including PGs and RCs, identified ZEB1 as a potential participant associated with STAT3 activation and Th17 cells in the pathogenesis of apical periodontitis." (PMID 40016707, 2025). "This study revealed that ZEB1 is a potential player correlated with STAT3 activation and Th17 cells in apical periodontitis pathogenesis." (PMID 40016707, 2025). "The study aimed to investigate the expression pattern of ZEB1 in Th17 cells and its colocalization with p-STAT3 in human apical periodontitis lesions." (PMID 40016707, 2025).
autoimmune disease (1 paper, 2010). A disorder resulting from loss of function or tissue destruction of an organ or multiple organs, arising from humoral or cellular immune responses of the individual to their own tissue constituents. "Concordingly, a SNP in ZEB1 has recently been suggested to associate with rheumatoid arthritis, another autoimmune disease." (PMID 20856809, 2010).
bladder papilloma (1 paper, 2022). "Previous investigations in static cell monolayers using RT4 bladder papilloma cells suggest that Nrf2 upregulation enhances the expression of both epithelial and mesenchymal markers (e.g., E-cadherin and ZEB1) while Nrf2 downregulation results in the attenuation of both markers." (PMID 35480877, 2022).
bullous keratopathy (1 paper, 2023). "ZEB1 was also a differentially expressed gene in ex vivo bullous keratopathy samples compared to control corneal endothelial samples." (PMID 37441688, 2023).
Burkitt lymphoma (1 paper, 2021). A rare form of malignant mature B-cell non-Hodgkin lymphoma. "Contrary to the mRNA, the expression of ZEB1 and ZEB2 protein was upregulated in Burkitt lymphoma cells upon exposure to HIV-1, supporting the notion that the enhanced migration of BL cells via downregulation of hsa-miR-200c-3p leads to an alleviation of active repression of the ZEB proteins." (PMID 34573283, 2021).
carcinosarcoma (1 paper, 2025). A malignant tumor composed of a mixture of carcinomatous and sarcomatous elements. "EMT-associated transcription factors, including Snail1, SIP1, ZEB1, Twist1, and Slug, have been detected in carcinosarcomas, yet their expression patterns lack consistency, even among samples originating from the same organ." (PMID 41367455, 2025).
cardiomyopathy (1 paper, 2022). A disease of the heart muscle or myocardium proper. "DOX upregulates miR-200c, which downregulates ZEB1 (zinc finger e-box binding homeobox 1), endothelial nitric oxide synthase, Sirtuin1 (SIRT1), and Forkhead boxO1, leading to epithelial dysfunction and DOX-related cardiotoxicities such as cardiomyopathy, cardiac apoptosis, and CHF." (PMID 35246252, 2022).
cyst (1 paper, 2025). A sac-like closed membranous structure that may be empty or contain fluid or amorphous material. "Given that molecular mechanisms driving epithelial cell proliferation are considered critical for cyst formation, we hypothesized that the upregulation of ZEB1 expression in epithelial cells of RCs may be related to its role in promoting the formation of the cyst wall." (PMID 40016707, 2025).
developmental arrest (1 paper, 2022). "In recent years, abnormal expression of Zeb1 has been found in many tissues and can affect the incidences of fetal developmental arrest and deformity." (PMID 35611144, 2022).
embryonal carcinoma (1 paper, 2022). A non-seminomatous malignant germ cell tumor characterized by the presence of large germ cells with abundant cytoplasm resembling epithelial cells, geographic necrosis, high mitotic activity, and pseudoglandular and pseudopapillary structures formation. "Further, our results also supported that Zeb1 played an important role in regulating the invasive ability of mouse embryonal carcinoma cells." (PMID 35611144, 2022). "When Zeb1 was knocked down, mouse embryonal carcinoma cell lines (P19) exhibited a 51.23 and 49.85% reduction in invasion capacity compared with the negative control and wild type, respectively." (PMID 35611144, 2022). "In the present study, it is showed that knockdown of Zeb1 inhibited embryonal carcinoma P19 cell invasion." (PMID 35611144, 2022). "We found that Zeb1 promoted the invasive ability of mouse embryonal carcinoma cells." (PMID 35611144, 2022). "We also found that Zeb1 could promote the invasive ability of mouse embryonal carcinoma cells in mESCs differentiation model." (PMID 35611144, 2022).
embryonic cancer (1 paper, 2022). "The results indicated that Zeb1 expression significantly decreased during normal differentiation of ESCs (P < 0.001), whereas the expression level of Zeb1 in P19 embryonic cancer cells is significantly higher than that in mESCs (P < 0.001)." (PMID 35611144, 2022).
emphysema (1 paper, 2019). "YY1 and ZEB1 also appeared as the regulators of the CCP formed between LC and Emphysema, giving another layer of evidence of their importance in the establishment of LC in patients with an emphysema antecedent." (PMID 31867044, 2019).
endometrial tumor (1 paper, 2016). "We found increases in SLUG, ZEB1, and HMGA2 mRNA expression in the myoinvasive front of tumor samples, indicating the role of these transcriptional factors in endometrial tumor progression and invasion." (PMID 27429042, 2016).
endometrioid carcinoma (1 paper, 2025). "FAM64A correlates with neither ZEB1, ZEB2 nor Snail1 in high-grade serous OC and endometrioid carcinoma." (PMID 40424038, 2025).
endometrioid endometrial carcinoma (1 paper, 2020). "When compared with the normal endometrium, SNAI1 was upregulated as early as in the noninvasive (stage 1A) and myoinvasive (stage 1B) tumors, followed by the expression of TWIST1, ZEB1, and SNAI2 in the myoinvasive (stage 1C) tumors of endometrioid endometrial carcinoma." (PMID 32370157, 2020).
endometrioid tumor (1 paper, 2021). A benign, borderline, or malignant epithelial tumor of the female reproductive system characterized by the presence of glands and/or cysts lined by neoplastic cells that resemble endometrial cells. "Reduced expression of CDH1 and KRT18 was significantly associated with high-grade tumors and non-endometrioid tumor histology, while increased expression CTSB, CDH2 and ZEB1 could be observed in serous tumors." (PMID 34936030, 2021).
Erythema (1 paper, 2023). Redness of the skin, caused by hyperemia of the capillaries in the lower layers of the skin. "imiquimod treatment resulted in reduced Zeb1 expression in the ear sections of Zeb1WT mice, and it led to greater erythema and epidermal thickening in the ears of Zeb1∆M mice compared to Zeb1WT mice." (PMID 37978290, 2023).
esophageal adenocarcinoma (1 paper, 2023). A malignant tumor with glandular differentiation arising predominantly from Barrett mucosa in the lower third of the esophagus. "Interestingly, the cell line expression data did not recapitulate the VIP and ZEB1 associations seen in healthy and cancer tissues and showed only a statistically significant association between VIP and ZEB1 in a limited number of esophageal adenocarcinoma cases (p = 0.05)." (PMID 37444395, 2023).
hemangioma (1 paper, 2021). A benign vascular lesion characterized by the formation of capillary-sized or cavernous vascular channels. "The authors found that 100 nM of BBP can significantly trigger the migration and invasion of hemangioma cells, also inducing the overexpression of Zeb1, a powerful transcription factor for cell migration and invasion, via miR-655 suppression or downregulation." (PMID 34199666, 2021).
insulinomas (1 paper, 2018). "Here it is shown that miR-200 ablation in the Rip-Tag2 insulinoma mouse model induces beta-cell dedifferentiation, EMT and tumor invasion, and that disruption of Zeb1 regulation by miR-200c is sufficient to drive EMT." (PMID 30405106, 2018). "In this regard, it would be interesting to investigate the regulation of miR-200, Zeb1 and their targets in the progression of human insulinomas to metastatic, nonfunctional pancreatic neuroendocrine tumors (PanNET)." (PMID 30405106, 2018).
intestinal cancer (1 paper, 2021). "This post-translational upregulation of Zeb1 is critical to RP11-induced dissemination of intestinal cancer cells." (PMID 33718238, 2021).
islet-cell carcinomas (1 paper, 2018). "This partial rescue thus further highlighted the significance of tuning Zeb1 expression in the process of dedifferentiation and invasion of islet-cell carcinomas." (PMID 30405106, 2018).